PML (PML nuclear body scaffold)
Diseases named in the same sentence as PML in open-access papers (continued):
Sharing a sentence is not in itself a finding about the gene and the disease.
leukemia (continued). "PML was shown to be indispensable for quiescent leukemia-initiating cell (LIC) function; loss of PML resulted in both LIC and hematopoietic stem cell (HSC) depletion." (PMID 23936764, 2013). "The heterogeneous telomere lengths and the detection of ALT-associated PML bodies (APBs) indicated that the ALT mechanism was mainly responsible for telomere maintenance in c-Myc-induced leukemias." (PMID 24202323, 2013). "Since the discovery of Promyelocytic leukemia (PML), this protein has been associated with the pathogenesis of several hematopoietic malignancies and solid tumors." (PMID 23936764, 2013). "While IGFBP2 is expressed at high levels by M3 t(15:17) APL cells that produce a fusion protein promyelocytic leukemia-retinoic acid receptor α (PML-RARA), the physiologic PML-RARA expression from the mouse pml locus rarely causes leukemia development." (PMID 24191913, 2013). "Since PML seemed to be a key regulator underlying leukemia and other cancers, these initial findings motivated a series of studies aimed at ascertaining its regulatory cues and functions." (PMID 23936764, 2013). "Both Suz12 and Znf198 associate with promyelocytic leukemia (PML) nuclear bodies (NBs); Suz12 and Znf198 knockdown cell lines exhibit reduced numbers of PML NBs." (PMID 23507839, 2013). "SP100 and ZNF451 are both components of promyelocytic leukemia (PML) bodies, which are implicated in interferon-induced antiviral defenses." (PMID 22291592, 2012). "Specifically, we identified cancers of multiple organ origins to be associated with PML expression including breast, colon, prostate, leukemia, embryoma, liver, lung, brain, melanoma, endometriosis, stomach, and ovarian cancers." (PMID 22947142, 2012). "Assembly of heterochromatin is often undertaken in promyelocytic leukemia (PML) bodies, and pRB and E2Fs are associated with PML in senescence." (PMID 22417103, 2012). "Latent HSV-1 genomes display two major patterns, called “Single” and “Multiple”, which associate with centromeres, and with promyelocytic leukemia nuclear bodies (PML-NBs) as viral DNA-containing PML-NBs (DCP-NBs)." (PMID 22912575, 2012). "The functional role of HDAC3 in leukemia has been attributed to its association with the PML–RAR fusion protein in a deacetylase-dependent fashion." (PMID 19204783, 2009). "However, some relapsed patients develop resistance to ATO due to mutations in the promyelocytic leukemia (PML) part of the PML::RARα fusion gene." (PMID 40330660, 2025). "Furthermore, primary leukemia cells from AML patients expressing mutated NPM1c also exhibit aberrant PML body formation." (PMID 37388925, 2023). "Interestingly, the effect of ATRA‐induced differentiation is insufficient for APL eradication, whereas only PML/RARA loss fully extinguish leukaemia‐initiating activity." (PMID 35001521, 2022). "The PML (promyelocytic leukemia) protein, a tumor suppressor protein that is frequently implicated in leukemia, is best known for its translocation with the retinoic acid receptor alpha (RARa) resulting in the PML-RARa protein, and for the organization of PML nuclear bodies." (PMID 33670160, 2021). "In support of ALT activation in our cell models, we detected ALT-associated hallmarks in H3.3G34RAPT-tKO cells including telomeric C-circle DNA 29, sister chromatin exchange (examples of TSCE are shown), and large ALT-associated promyelocytic leukaemia (PML) bodies (APBs)." (PMID 33972520, 2021). "PML-RAR is a fusion gene that is associated with the specific subtype of leukemia APL." (PMID 34074803, 2021). "We set the cutoff of the signal binding normalized scores (in the range of 0–1000) to 350 and identified promyelocytic leukemia (PML), cyclin T2 (CCNT2) and MYC-associated zinc finger protein (MAZ) as binding to both the +157 enhancer and the promoter of the VEGFA gene." (PMID 34316716, 2021).
leukemia (continued). "In particular, the PML-RARα leukemia is caused by aberrant expression of PML-RARα fusion protein." (PMID 32429325, 2020). "Indeed, promyelocytic leukemia nuclear bodies (PML-NBs), discrete nuclear speckles tightly associated with the nuclear matrix and implicated in cellular senescence, have a nuclear arrangement that is influenced by A-type lamin deficiency." (PMID 30362963, 2018). "Thus, this evidence suggests that fusion-circRNAs, as products of the PML-RARα fusion gene, are very likely to be a diagnostic biomarker or therapeutic target in leukaemia." (PMID 28535767, 2017). "This PML-RAR-α fusion protein plays a causal role during leukemia development in mouse models." (PMID 23460888, 2013). "Loss of PML in cancers from multiple origins underlines its tumor-suppressive role beyond leukemia." (PMID 23936764, 2013). "Interestingly, Net1 colocalizes with these proteins in discrete punctate nuclear structures that are associated with promyelocytic leukemia (PML) bodies." (PMID 21390328, 2011). "SP100 is a subunit of promyelocytic leukemia nuclear bodies (PML-NBs) and binds to heterochromatin protein 1 (HP1), contributing to transcriptional repression and chromosomal architecture." (PMID 41188771, 2025). "As interferon-inducible proteins, SP family members are highly expressed in innate and adaptive immune cells (with SP140 expression being immune-restricted) and localize to promyelocytic leukemia nuclear bodies (PML-NBs)." (PMID 41188771, 2025). "ALT cancer cells exhibit associations between the promyelocytic leukemia nuclear bodies (PML-NBs) and telomeres, forming the ALT-associated PML-NBs (APBs)." (PMID 38752489, 2024). "The ELN also stipulates suitable molecular biomarkers, highlighting leukemia initiating variants (e.g., NPM1, CBFB::MYH11, RUNX1::RUNX1T1, PML::RARA) essential in disease monitoring." (PMID 38891959, 2024). "The PML-RARα fusion protein was degraded after treatment of primary leukemia cells with 100 and 150 μM catechin for 24 h." (PMID 38566147, 2024). "In comparison to APL with PML::RARA, APL-like AML with NPM1 mutation exhibits leukemia cells with lower SSC, frequent expression of CD4, and higher white blood cell counts." (PMID 39432585, 2024). "The success of arsenic in degrading PML‐RARα oncoprotein illustrates the great anti‐leukemia value of inorganics." (PMID 37888866, 2023). "Isoforms of promyelocytic leukemia (PML)/TRIM19 proteins also range from 48–97 KDa conferring apoptotic and antiviral activities." (PMID 36980939, 2023). "In chronic myeloid leukemia, PML promotes stemness in hematopoietic cells, favoring the maintenance of leukemia-initiating cells." (PMID 37382966, 2023). "Genomes with chromosomal rearrangements can also produce fusion circular RNAs (f-circRNAs) by backsplicing of chimeric transcripts, as first shown in leukemias with PML::RARα and KMT2A::MLLT3 translocations and later in solid cancers." (PMID 36585787, 2023). "The promyelocytic leukemia nuclear bodies (PML-NBs) are proteinaceous nuclear structures with instrumental roles in regulation of various stress-induced responses including senescence." (PMID 37019904, 2023). "Reductions in cellular levels of NRF2 seem to be independent of proteasomal degradation and the interferon/promyelocytic leukemia (IFN/PML) pathway." (PMID 37022178, 2023). "In genetically engineered mouse models, the WDR4/Promyelocytic leukemia (PML) axis elevates intratumoral Tregs and M2-like macrophages and reduces CD8+ T cells to promote lung tumor growth." (PMID 36816047, 2023).
leukemia (continued). "Treatment with arsenic trioxide (ATO) can overcome this differentiation block by first promoting PML-NB re-formation and subsequent degradation to facilitate clearance of leukemia cells." (PMID 38066546, 2023). "Previous studies reported that the SMC5/6 complex colocalizes with scaffold proteins of promyelocytic leukemia (PML) bodies (PML and SP100)." (PMID 37338350, 2023). "Biologically, mice transgenic for the fusion gene PML::RARA manifested a pre-leukaemic state of deranged myeloid maturation, with an APL-like leukaemia only developing if collaborating mutations such as internal tandem duplication of FLT3 were present." (PMID 36765318, 2023). "Some TRIM genes are often transferred to other genes to produce fusion proteins involved in cancer initiation and progression, the most famous of which is the promyelocytic leukemia gene PML, which encodes TRIM19." (PMID 36249749, 2022). "All-trans-retinoic acid (ATRA) predominantly promotes oncoprotein PML-RARα knockdown to eliminate AML M3 leukemia cells, and this can significantly improve the prognosis of M3 patients." (PMID 36002858, 2022). "Promyelocytic leukemia (PML) nuclear bodies (PML-NBs) are membrane-less organelles that are formed by phase separation and are present in the nuclei of mammalian interphase cells." (PMID 35579421, 2022). "ALT positive U2 OS cancer cells are characterized by promyelocytic leukemia (PML) bodies and high frequency of T-SCE, indicative of telomere recombination, and show extremely long telomeres: even longer than those of human ES cells." (PMID 35159266, 2022). "One such heterochromatin binding protein is pro-myelocytic leukemia-nuclear bodies (PML-NBs) which has been shown to be significantly correlated with DNA damage associated senescence in ageing mice." (PMID 36241685, 2022). "Herpes simplex virus-1 (HSV-1) infection results in a three-fold decrease in the modification of over 100 cellular proteins, including the anti-viral promyelocytic leukemia (PML) nuclear bodies PML." (PMID 35215907, 2022). "The macromolecular multiprotein complexes known as promyelocytic leukemia nuclear bodies (PML NBs) are an archetype for nuclear membrane-less organelles." (PMID 35742810, 2022). "Here, we show the presence of ALT-associated promyelocytic leukemia bodies (APBs), TRF2, pT371-TRF1 and for the first time the colocalization of pT371-TRF1 and PML in three patient-derived Hodgkin lymphoma cell lines in both HL and RS cells." (PMID 36140400, 2022). "The main components of PML bodies in human cells are the six nuclear isoforms of the protein of promyelocytic leukemia (PML) formed via alternative splicing, therefore, they differ in size and amino acid sequence of their C-terminal domains." (PMID 36291650, 2022). "For example, in leukemias and prostate cancer, promyelocytic leukemia (PML) plays a critical regulatory role by inhibiting HAUSP activity through death domain-associated protein (DAXX), which in turn favors PTEN nuclear localization." (PMID 36385557, 2022). "Here we demonstrate that PML is essential for oxidative stress-driven partner SUMO2/3 conjugation in mouse ESCs (mESCs) or leukemia, a process often followed by their poly-ubiquitination and degradation." (PMID 36175410, 2022). "Studies have also indicated that HCMV IE1 protein inhibits the transcription of ISGs by sequestering its binding of promyelocytic leukemia (PML) and STAT2, thus decreasing IFN responses while increasing IFN-β tolerance in the virus." (PMID 34305856, 2021). "Promyelocytic leukaemia nuclear body (PML-NB) contains three major components, PML, SUMO and UBC9, and functions as the main inducible factor of cellular senescence." (PMID 34255975, 2021). "In its E3 ligase capacity, UBE3A reportedly interacts with the tumor suppressor promyelocytic leukemia protein (PML) in leukemia, Burkitt's lymphoma, and prostate cancer 29-31." (PMID 34421347, 2021).
leukemia (continued). "A well-established example is the promyelocytic leukemia protein (PML), encoded by a tumor-suppressor gene implicated in leukemia." (PMID 32646031, 2020). "To determine how PML-RARα is involved in the metabolic disorders associated with APL, we examined the expression of PM-RARα and PPARγ in leukemia cells from APL patients." (PMID 32929351, 2020). "Fusion proteins actively contributing to carcinogenesis, as for example the fusion proteins AML1-ETO and PML-RARα in Leukemia." (PMID 31665520, 2020). "Promyelocytic leukemia (PML) bodies are liquid droplet-like structures organized by the eponymous PML proteins in the nuclei of our cells." (PMID 32365141, 2020). "This occurs along with the alternative lengthening of telomeres (ALT) and DNA repair by homologous recombination (HR) in the nuclear promyelocytic leukemia (PML) bodies." (PMID 32316332, 2020). "Promyelocytic leukemia (PML) bodies, also known as nuclear domain 10, are membrane-less nuclear organelles present in most cells." (PMID 32365141, 2020). "Further underscoring this, and in sharp contrast to its role in AML, on the background of the APL-typical PML-RARA fusion, the Flt3-ITD mutation reduced the inhibitory effect of atRA on the ability to initiate leukemia in secondary recipients." (PMID 32998330, 2020). "Retinoic acid and As2O3 cause transcriptional repression of PML-RARα leading to the growth arrest of LICs in mouse APL, thus indicating a positive role of PML-RARα in maintaining cancer stem cell (CSCs) in leukemia." (PMID 33396222, 2020). "We tested the platform by inducing knockdown of Zeb2, a gene upregulated by AML1-ETO and PML-RARα oncogenes in pre-leukemic hematopoietic stem cell compartment, and observed a significant delay in leukemia onset." (PMID 33327558, 2020). "PR-GFP-CRE mice constitutively express PML-RARα and, like the parental PR strain, developed leukemia spontaneously, with a latency of 10–14 months, and a penetrance of 70%." (PMID 33327558, 2020). "By confocal microscopy we detected significantly reduced numbers of promyelocytic leukemia (PML) bodies in HEK293 cells, stably expressing moderate amounts of FLAG-FAT10." (PMID 31575873, 2019). "ATO is approved by the FDA exclusively for the treatment of APL because it is the only leukemia that expresses the ATO presumed target PML-RARα." (PMID 30093655, 2018). "Even in APL, ATRA’s ability to activate RARs and induce leukemia cell differentiation can be uncoupled from its activity to induce PML-RARα degradation, inhibit APL stem cells, and treat APL20,21." (PMID 30093655, 2018). "This translocation leads to the fusion of the retinoic acid receptor-α (RARα) gene and promyelocytic leukemia (PML) gene, resulting in the formation of the PML/RAR-α fusion protein, which is involved in leukemogenesis." (PMID 30225259, 2018). "SAP25 is a member of the nucleocytoplasmic shuttling proteins that are located in promyelocytic leukemia (PML) nuclear bodies." (PMID 29236770, 2017). "We found that arrested EBV-infected B cells exhibited an increase in promyelocytic leukemia nuclear bodies (PML NBs), which predominantly localized to markers of DNA damage, as well as telomeric DNA." (PMID 29194355, 2017). "Recent studies have also shown that in leukaemia with PML/RARα translocations, a type of special fusion-circRNA can be generated during the generation of fusion-gene." (PMID 28535767, 2017). "Viral DNA is recognized by the promyelocytic leukemia-nuclear bodies (PML-NBs) (also referred to as ND10), an interferon-inducible nuclear structure consisting of core proteins PML, SP100, Daxx, and ATRX." (PMID 28792463, 2017). "In fact, the oncogenic fusion-protein (PML-RAR) typical of this leukemia contains the retinoid-nuclear-receptor RARα." (PMID 27419624, 2017).
leukemia (continued). "PCR and FISH analyses performed during diagnosis showed that patient OM110223’s leukemia cells present a short bcr3 transcript which connects exon 3 of the PML gene and exon 9 of the RARA gene (equivalent to the exon 3 of the RARA-001 ENSEMBL transcript)." (PMID 29623188, 2017). "Topoisomerase II administration is associated with known balanced translocations including the MLL (mixed-lineage leukemia) gene at 11q23 or PML/RARA (promyelocytic leukemia/retinoic acid receptor, alpha) gene." (PMID 26798525, 2015). "This enhancer also has interactions with the promoter of GALNT5 and appears to be bound by a number of factors in K562 including GATA2, PML, TAL1 and BCL3, all of which have been implicated in the leukemia or other forms of cancer." (PMID 26576536, 2015). "In the majority of PML-RARα+ AML patients, retinoic acid receptor alpha (RARα) is fused to the promyelocytic leukemia (PML) open reading frame on chromosome 15." (PMID 26179601, 2015). "Administration of As2O3 in leukemia induces the ubiquitination-mediated degradation of the PML-RARα fusion protein via multiple pathways and manifests substantial therapeutic effects." (PMID 26510911, 2015). "As PML has been shown to be a major target of As2O3 in cancer stem cells in leukemia, we sought to determine the regulatory relationship between PML and c-Myc in GSCs." (PMID 26510911, 2015). "Functional enrichment analysis of the top 1% of genes revealed many functions involved in leukemia development, such as ‘PML body organization’, ‘immune response-activating signal transduction’, and ‘transforming growth factor beta receptor signaling pathway’." (PMID 26169043, 2015). "To compare the cell population maintaining PML/RARα-positive leukemia with the L-IC population, we sorted the principal subpopulations for transplantation into sublethally irradiated recipients." (PMID 25568664, 2014). "In contrast to our model, these findings were obtained using an already established leukemia based on the expression of PML/RARα driven by promoters mainly active in committed progenitors, but also in the LT-HSC compartment, even at a lower level." (PMID 25568664, 2014). "Promyelocytic leukemia (PML) gene was discovered as a fusion partner of human retinoic acid receptor alpha (RARα) gene, resulting in PML-RARα fusion protein that is critical for pathogenesis of acute promyelocytic leukemia (APL)." (PMID 25419843, 2014). "Indications that PML regulates the biology of stem cells have come recently from two elegant and unrelated studies in which the function of PML was investigated in leukemia and hematopoietic stem cells, and in neural stem cells." (PMID 24575390, 2014). "We treated NB4 leukaemia cells that contain the PML-RARAα fusion with arsenic trioxide and compared the degradation of PML-RARα with that of endogenous PML." (PMID 24190887, 2014). "The established PML/RARα-positive leukemia was composed of 73% linlo/- cells, 65% of which were already committed Sca1−/c-Kit− cells, 13.5% were Sca1−/c-Kit+ and 1.5% presented the stem-cell phenotype of Sca1+/c-Kit+." (PMID 25568664, 2014). "All-trans retinoic acid (ATRA) has been successfully used as a leukemia therapy to target the transcriptional repression mediated by the PML-RARα fusion protein." (PMID 25245097, 2014). "To identify the cell population that maintains the PML/RARα- or RUNX1/RUNX1T1-positive leukemias, we transferred 2×104 cells from leukemic mice, with a tumor load of at least 80%, into sublethally irradiated secondary recipient mice." (PMID 25568664, 2014). "DEK/NUP214 and PML/RARα exert their leukemogenic potential on a very small subpopulation of HSC explaining the low penetrance of leukemia from PML/RARα- and DEK/NUP214-transduced HSPCs." (PMID 25568664, 2014).